STAT3 (signal transducer and activator of transcription 3)
Diseases named in the same sentence as STAT3 in open-access papers (continued):
Sharing a sentence is not in itself a finding about the gene and the disease.
tumor (continued). "Moreover, the most undifferentiated stem-like PC cells expressed the highest levels of IL-6 and IL-6R: blockade of JAK/STAT3 signaling could inhibit colony-forming and tumor initiation." (PMID 34830209, 2021). "Thus, we investigated the tumor suppressor role of knocking down circUBE2Q2 in vivo and whether combination of circUBE2Q2 knocking down and stattic (a common STAT3 inhibitor) could result in additive or synergistic effects on the growth of GC in vivo." (PMID 34611143, 2021). "Therefore, the CADM1/HER2/STAT3 axis has broad prospects for the treatment of tumor metastasis." (PMID 34395444, 2021). "This interaction can trigger the STAT3 (signal transducer and activator of transcription 3) pathway via phosphorylation of Tyk2 (tyrosin kinase 2) in B cells, with consequent induction of the immunoregulatory cytokines IL-10 and IL-6, which facilitates immune evasion and supports tumor growth." (PMID 35071240, 2021). "Additionally, STAT3 signaling is thought to be important for glial scar formation, suggesting the possibility that GAAs at the tumor periphery are attempting to contain the tumor, but their pro-tumor properties are hijacked instead." (PMID 34483843, 2021). "Therefore, targeting STAT3 signaling is along the encouraging direction of tumor immunotherapy." (PMID 34620838, 2021). "Overexpression of CLDN9 could promote tumor cell invasion through Tyk2/STAT3 signaling." (PMID 35223866, 2021). "Given that both L1CAM and activated STAT3 have been implicated in different tumor types, this paradigm might not be limited to OC." (PMID 34645505, 2021). "However, the role of STAT3 in epigenetic modifications of tumor suppressors is less explored." (PMID 33718136, 2021). "Therefore, targeting the IL-6/JAK/STAT3 pathway in patients with ONB might provide therapeutic benefit by directly suppressing tumor cell proliferation and restoring antitumor immunity, as already demonstrated in several other histotypes." (PMID 34064009, 2021). "Interestingly, in preclinical tumor models, siRNA-regulated expression of STAT3, STAT6, IKKβ HIF-1α proteins for TAM differentiation, and of CCR2 receptor for monocyte recruitment enriched the TIME of antitumor M1-like macrophages and reduced the number of immunosuppressive cells." (PMID 34150739, 2021). "Macrophage polarization may be reprogrammed to tumor cell killing by treatment with tyrosine kinase inhibitors sunitinib and sorafenib, or fenretinide [4-hydroxy (phenyl) retinamide], which inhibit STAT3 or STAT6 in macrophages, thereby blocking IL-10 secretion." (PMID 34831167, 2021). "Although all the STAT proteins have a pivotal role in cellular homeostasis, nowadays, the study of STAT3 has gained more importance because several functions of this protein have not yet been completely described and because it exerts many different functions in tumor growth and progression." (PMID 34440160, 2021). "Likewise, immunosuppression and tumor promotion are magically integrated into STAT3 cascade." (PMID 33957948, 2021). "Another subpopulation of astrocytes that displays high levels of the immune checkpoint PD-L1 and activation of the immunomodulatory factor STAT3 has also been observed in the peritumoral area, where it might constitute a barrier against anti-tumor T lymphocytes." (PMID 34690699, 2021). "Interestingly, this result indicated that the IL6/JAK/STAT3/SIGNALING pathway may be a potential pathway for explaining how genomic instability-derived lncRNAs affected tumor progression." (PMID 34712264, 2021). "Therefore, LL1 inhibits tumor growth and invasion by blocking STAT3 signaling pathway." (PMID 34059647, 2021). "Interestingly, elevated oxidative stress in mouse embryonic fibroblasts promotes STAT3 phosphorylation and its translocation to the nucleus independently of cytokines, which may subsequently promote tumor cell survival." (PMID 34858425, 2021).
tumor (continued). "Moreover, TNF-α derived from TAMs could stimulate tumour cells to release IL-6, contributing to STAT3 activation in TAMs." (PMID 33654093, 2021). "Consequently, uncontrolled (prolonged or constitutive) activation of STAT3 may lead to dysregulation of target gene expression, thereby promoting malignant transformation and tumor cell survival." (PMID 34884773, 2021). "In addition to promoting the infiltration of immune cells into the tumor, IL-6 has also been reported to enhance STAT3 phosphorylation, which increases anti-apoptosis of tumor cells; specifically, overexpressed IL-6 has been identified as a marker of malignancy in GBM." (PMID 34337348, 2021). "Constitutive activation of STAT3 initiates transcription of a range of downstream oncogenes, such as β-catenin (encoded by CTNNB1) in the Wnt pathway and nuclear factor-κB (NF-κB), frequently hyperactivated in cancer to promote tumor growth or pro-oncogenic inflammation." (PMID 33805945, 2021). "Accordingly, phosphorylated STAT3 expression could also be used as a guide to measure EGFR activity and identify patients that may not necessarily have EGFR mutations, but still depend on EGFR signaling for tumor cell proliferation and survival." (PMID 34944848, 2021). "Moreover, cytokines regulated by STAT3 in tumor microenvironment, like IL-6, IL-10, VEGF and TGF-β, trigger a positive feed-back amplification of STAT3 in multiple types of cells throughout the tumor microenvironment, finally resulting in severer tumor growth and immuno-suppression." (PMID 34502195, 2021). "In addition, it has been illustrated that STAT3 could make a contribution to carcinogenesis and tumor progression by the way of increasing gene expression." (PMID 34165442, 2021). "Therefore, STAT3 inhibition has been extensively explored to reduce tumour growth and metastasis." (PMID 33546207, 2021). "Moreover, HIF1α upregulation together with stable or downregulated STAT3 may have implications for tumor growth as HIFα can hamper tumor growth." (PMID 33815383, 2021). "Therefore, STAT3 might maintain tumor growth after irradiation through MSI1-mediated attenuation of miR-671-5p." (PMID 35052701, 2021). "Thus, cinobufagin inhibits EGFR and STAT3 signaling to block tumor growth in nude mice." (PMID 34925034, 2021). "However, in an already established tumor, the maturation of myeloid cells to macrophages is blocked by multiple factors and mechanisms, such as tumor-derived growth factors (STAT3, IRF8, C/EBPβ, Notch, adenosine receptors A2B signaling, NLRP3), hypoxia, and negative feedback loops." (PMID 34557407, 2021). "However, it remains unclear whether STAT3 inhibition influences the anti-tumor activity of Hsp90 inhibitors." (PMID 33390934, 2020). "Therefore, recent data suggests that IL-6/JAK/STAT3 signaling pathway may represent a therapeutic target to suppress tumor growth and activate the antitumor immune response." (PMID 33080912, 2020). "Thus, STAT3 is considered a promising target in the development of anti-tumor drugs." (PMID 32872659, 2020). "However, other modes of action of PTPRK, such as dephosphorylating other signaling factors like β-catenin, EGFR, or STAT3, or cell junction proteins, may also contribute to its tumor-suppressive function." (PMID 31934854, 2020). "Moreover, TGF-β in the tumor microenvironment triggers the expression of TIM-3 on the surface of TAMs and subsequent IL-6 secretion; the TAM-derived IL-6 further activates the IL-6/signal transducer and activators of transcription (STAT3) pathway in the tumor, sustaining survival and proliferation." (PMID 32722054, 2020). "In brief, excessive STAT3 activity in innate immune cell subsets may impair the production of pro-inflammatory mediators such as IFNγ, dampen antigen presentation, and inhibit the tumor-killing activities of effector cells." (PMID 32972405, 2020).
tumor (continued). "In PDAC, activation of JAK2/STAT3 cell signaling with the participation of REG3G was found to induce immunosuppression by limiting the antigenicity of tumor cells, suppressing CD8+ cell function, causing variable expression of Th2 cytokines and increasing the proliferation of tumor cells." (PMID 32488850, 2020). "STAT3 may be activated by cytokines such as IL-6 and IL-10 that, released by tumor cells, besides acting in an autocrine fashion to sustain cancer cell survival, may activate this pathway in myeloid immune cells in the tumor environment, resulting in an impairment of their function." (PMID 32754441, 2020). "Thus, inhibition of STAT3 in cDC1s may provide an important strategy to improve their efficacy in tumor vaccination approaches and cDC1-mediated control of anti-tumor immunity." (PMID 31947933, 2020). "Collectively, these data suggest that Mifamurtide, switching macrophage polarization towards a TAM-like intermediate M1/M2 phenotype and reducing IL-17R levels and STAT3 activation, may inhibit the cellular proliferation and induce the tumor cell differentiation." (PMID 32133045, 2020). "By activating STAT3, TAMs and small‐cell lung cancers could jointly promote tumour progression." (PMID 32618105, 2020). "Furthermore, activated STAT3 is a critical regulator of cell energy metabolism, which could have a significant impact on tumor transformation and growth." (PMID 33182552, 2020). "Our work indicates that disruption of the vicious circle involving STAT3 signaling in the tumor microenvironment, along with the stimulation of TLR7/8 signaling, could induce effective antitumor immune responses without toxicity and chemotherapy-associated side effects." (PMID 33679700, 2020). "Thus, we concluded that astaxanthin inhibits DU145 tumor cells by reducing the level of STAT3." (PMID 32784629, 2020). "However, STAT3 may also function as a tumor suppressor in NSCLC and other solid malignancies, depending on the tumor driver and cellular context." (PMID 32365499, 2020). "This may provide a new theory for STAT3 in promoting tumor cell growth." (PMID 32911343, 2020). "Similarly, STAT3 drives the acquisition of pro-tumor functions of adaptive immunity." (PMID 33584695, 2020). "Finally, we will discuss a vast therapeutic potential for the STAT3-inhibiting single-agent treatment innovation that, as the desired outcome, could block tumor growth and generally prevent muscle cachexia." (PMID 33158194, 2020). "Interestingly, a recent study reported that ablating STAT3 in CD8+ T cells prior to the CD8+ T cell transfer allows for efficient CD8+ T cell tumor infiltration and robust proliferation, resulting in increased tumor antigen-specific T cell activity and tumor growth inhibition." (PMID 32503584, 2020). "Therefore, STAT3 is considered to be a target molecule in several tumor types." (PMID 32256354, 2020). "Importantly, the decoy oligonucleotide retained its potent effects on STAT3 activity and could inhibit tumour growth of HNSCC in vivo." (PMID 32899142, 2020). "The use of GBM cells and fluorescent marked macrophages, along with the determination of pSTAT3 in co-cultures, could better illustrate a bidirectional STAT3/miR-21-mediated relationship, arguing for the use of STAT3 inhibitors in tumor microenvironment modulation." (PMID 32178454, 2020). "Interestingly, it has been shown that loss of STAT3 or STAT5 promotes cancer growth in certain tissues, suggesting these STAT proteins might function as tumor suppressors in these situations." (PMID 32087696, 2020). "However, blockade of STAT3 signaling may result in an impairment of tumor immune surveillance and STAT3 may act as a tumor suppressor, particularly in the context of K-RAS-driven lung tumorigenesis." (PMID 32365499, 2020).
tumor (continued). "Therefore, we believe the primary action of tumor-derived IL-17A in tumor-bearing mice is to induce a rapid expansion of myeloid cells, including neutrophils and MDSCs, via the production of STAT3-activating cytokines including IL-6, G-CSF, and GM-CSF by tumor cells." (PMID 32770025, 2020). "Notably, strong colocalization was observed in tumour tissue from the control group, whereas sanguinarine treatment significantly altered the subcellular localization of p‐STAT3‐Tyr and especially p‐STAT3‐Ser, and potently inhibited the colocalization of HIF‐1α/p‐STAT3‐Tyr and HIF‐1α/p‐STAT3‐Ser." (PMID 32065498, 2020). "Therefore, while in vitro treatment with LIF may stimulate tumor cell proliferation, its ability to stimulate STAT3 signaling in the context of the bone microenvironment may still promote tumor dormancy, although the mechanism is unresolved." (PMID 32023849, 2020). "Therefore, we further verified by WB, qPCR, and other techniques whether BEL may inhibit tumor cell growth through the STAT3/COX-2 pathway." (PMID 33299414, 2020). "FGFR4-Arg388 could activate ERK, c-scr and STAT3 signaling, contributing to tumor progression." (PMID 32154250, 2020). "Besides, we described how anti-tumor compounds are able to modulate STAT3." (PMID 32545648, 2020). "STAT3 activation has been reported to contribute to MM progression both directly, by upregulating survival and anti-apoptotic target genes, as well as indirectly by activating myeloid-derived suppressor-cells (MDSCs) in the bone marrow microenvironment, which facilitates tumor progression." (PMID 31963765, 2020). "Moreover, HJC0152 reduced expression of p‐STAT3 (Tyr705), Ki67 and cleaved caspase‐3 in tumours." (PMID 32022328, 2020). "Compared to the control, the protein expression levels of STAT3, p-STAT3Ser727, p-STAT3Tyr705, Bcl2, cyclin D1, and c-myc were lower in the Stattic and CTS-treated groups, indicating that STAT3 might be important for tumor development and progression in TA2 SBC." (PMID 32432040, 2020). "However, knockout ERK5 in TAMs reduces the phosphorylation of STAT3 and inhibits its M2 phenotype, which promotes the anti-tumor activity of TAMs, thereby inhibiting the melanoma growth, which suggests that targeting ERK5 is an attractive cancer treatment strategy." (PMID 33224886, 2020). "Moreover, STAT3 has also been proved to be the target of tumor therapy." (PMID 32883354, 2020). "Thus, the combination of astaxanthin and si-STAT3 improved the anti-tumor effects." (PMID 32784629, 2020). "Therefore, the subcellular localization of STAT3 directly guides canonical and non-canonical pathways that are involved in tumorigenesis and tumor-induced reprogramming of immune system, highlighting STAT3 as a primary target to build up effective immunotherapeutic strategies." (PMID 33584695, 2020). "Moreover, STAT3 expression in tumor cells may also enhance the expression of Rab family proteins, which facilitates exosome release to confer cisplatin resistance in ovarian cancer." (PMID 33153193, 2020). "STAT3 may have tumor promoting activity in MB by upregulating prometastatic molecules." (PMID 32992699, 2020). "Accumulating evidence has shown that Signal Transducer and Activator of Transcription 3 (STAT3) is thought to be a promising target for cancer therapy as STAT3 is frequently overexpressed in a wide range of cancer cells as well as clinical specimens, promoting tumor progression." (PMID 31949487, 2020). "IL-6 is an important inflammatory cytokine secreted by tumor cells or stromal cells, which is highly expressed in some tumors, and participate in a variety of malignant biological processes by activating a variety of signal pathways, such as STAT3, ERK and MAPK." (PMID 33153467, 2020).
tumor (continued). "Although the mechanisms of astaxanthin mediating anti-cancer action have not yet been fully clarified, a number of molecular targets of astaxanthin have been proposed, which may explain the anti-tumor effects of this drug, such as NF-κB, STAT3, PI3K/AKT, MAPKs, PPARγ, and so on." (PMID 32784629, 2020). "Additionally, combination therapy such as lumbar-punctured RES with neurosurgery significantly improved the prognosis of rats with advanced orthotopic GBM, prolonged the postoperative survival time, suppressed tumor growth, induced apoptosis, and inactivated STAT3 signaling." (PMID 31963897, 2020). "Additionally, TGF-β secreted by CAFs can induce STAT3 signalling in tumour cells." (PMID 33037194, 2020). "Hence, STAT3 is expected to become a novel tumour therapeutic target." (PMID 32636937, 2020). "In addition, NF-κB may present a unique target for tumor avoidance and therapy in combination with inhibition of transcription factors, such as Stat3." (PMID 33381179, 2020). "CXCL9 treatment could significantly increase the STAT3 activity in the PAAD tumour of mice." (PMID 31913856, 2020). "As mentioned, niclosamide has been recently identified as the small molecule inhibitor of STAT3, the member of a signaling pathway that regulates many cellular processes important for tumorigenesis, including cell proliferation, cell cycle progression, apoptosis, or tumor angiogenesis." (PMID 32408543, 2020). "Moreover, a lysine methyltransferase, EZH2 as a part of the EZH2-containing PRC2 complex, maintain gene silencing through hypermethylation of tumor suppressors, and p-AKT-induced EZH enhances tumor progression through activation and methylation of STAT3 by direct association." (PMID 31952344, 2020). "The reported discrepancies for the function of STAT3 in CD8 T cell mediated anti-tumor responses may rely on distinct roles of this TF depending on the T cell differentiation state (effector versus memory), the combined immunotherapy regimen and the STAT3-inducing cytokines in the TME." (PMID 31766350, 2019). "Therefore, those miRNAs above regulated tumor MDSCs plasticity through inhibiting STAT3 pathways." (PMID 31413755, 2019). "In addition, STAT3-mediated transcriptional regulation of inducible nitric oxide synthase (iNOS) has been detected in GBs with activated EGFR III variant (EGFRvIII), and was associated with tumor growth and invasive potential." (PMID 31698775, 2019). "Moreover, STAT3 promotes immunosuppression in the tumor microenvironment." (PMID 31671769, 2019). "The tumour-bearing group had increased serum WF content, and the skeletal-muscle showed a reduction in IRS-1 and RAG activation, increased PKB/Akt and Erk/MAP4K3 on the 21st day, and maintenance of p70S6K1, associated with increases in muscle STAT-3 and STAT-6 levels in these tumour-bearing rats." (PMID 30975087, 2019). "Moreover, tumor-associated CD19+ B cells expressing the activated signal transducer and activator of transcription 3 (STAT3) can produce vascular endothelial growth factor (VEGF) at the tumor site, which leads to an increased angiogenesis and supports tumor progression." (PMID 31086070, 2019). "The STAT3 axis was then more specifically targeted with an intravenous injection of a STAT3–small interfering RNA (siRNA)–CpG conjugate which was shown to silence the immune suppressor gene STAT3, reprogramming the functions of TAMs correlated with an immune-mediated tumor rejection." (PMID 31547627, 2019). "Moreover, notable activation of Stat3 may potentiate the deleterious effect of doxorubicin-induced senescence, since this signaling pathway mediates immune suppression in tumor." (PMID 30871042, 2019).